NF1 (neurofibromin 1)
Diseases named in the same sentence as NF1 in open-access papers (continued):
Sharing a sentence is not in itself a finding about the gene and the disease.
malignant peripheral nerve sheath tumor (continued). "Inactivating NF1 mutations cause hyperactivation of RAS-mediated signaling, resulting in the development of multiple neoplasms, including malignant peripheral nerve sheath tumors (MPNSTs)." (PMID 38502231, 2024). "If articles about benign schwannomas are put in a separate category, little is written about NF-1-related malignant schwannomas of the sciatic nerve." (PMID 38013269, 2023). "When articles about benign schwannomas are placed in a separate category, little is written about NF-1-related malignant schwannomas of the sciatic nerve." (PMID 38013269, 2023). "Interestingly, somatic mutations in NF1 are observed in 5–10% of cancers, including sarcomas such as malignant peripheral nerve sheath tumors (MPNST), brain and breast cancers, juvenile myelomonocytic leukemia, and Watson syndrome." (PMID 37147639, 2023). "Germline mutations of NF1 cause neurofibromatosis type 1 (NF1) through the activation of the RAS signaling pathway, and some NF1 patients develop malignant peripheral nerve sheath tumors (MPNSTs)." (PMID 35625983, 2022). "In addition, NF1 is a tumor suppressor gene; NF1 mutation was first demonstrated in the malignant peripheral nerve sheath tumor (MPNST), which is a subtype of STSs." (PMID 35559021, 2022). "Malignant peripheral nerve sheath tumor (MPNST) is the most common and serious malignant tumor based on NF1, and the risk of developing it in a lifetime is reported to be 5.9–15.8%9–11." (PMID 34099792, 2021). "Multiple neurofibromas can be associated with neurofibromatosis type I (NF-1) and, a small rate of patients can develop malignant peripheral nerve sheath tumors (MPNST) with dismal clinical outcome; the cumulative lifetime risk of developing MPNST in patients with NF1 is about 8–13%." (PMID 32676456, 2020). "Our in vitro findings showed that mebendazole (MBZ) inhibits the growth of NF1-related malignant peripheral nerve sheath tumors (MPNSTs) through a reduction in activated guanosine triphosphate (GTP)-bound Ras." (PMID 32650362, 2020). "We have found that erbB receptor tyrosine kinases drive Ras hyperactivation and growth in NF1-null malignant peripheral nerve sheath tumors (MPNSTs)." (PMID 31291965, 2019). "The first case of a female patient with NF1 and a breast malignancy identified in this study was reported in 1933 by Arthur Jackson, where a 52 year old female with a neurogenic sarcoma of the left breast was presented." (PMID 30962859, 2019). "Patients with malignant peripheral nerve sheath tumor (MPNST), a rare soft tissue cancer associated with loss of the tumor suppressor neurofibromin (NF1), have poor prognosis and typically respond poorly to adjuvant therapy." (PMID 28556483, 2017). "Although NF1 is known to play a role in the development of malignant peripheral nerve sheath tumors (MPNSTs), its role in modulating glutamine dependency has not been studied before." (PMID 29212209, 2017). "This tumor type appears to be restricted to generalized or mosaic NF1 and is said to rarely develop into malignant peripheral nerve sheath tumor (MPNST)." (PMID 29214122, 2017). "The combination of PRC2 inactivation and oncogenic RAS pathway activation now has been observed in several contexts: NF1-associated malignant peripheral nerve sheath tumors (MPNST), juvenile myelomonocytic leukemia (JMML), megakaryocytic AML of Down syndrome, and ETP-ALL." (PMID 27242978, 2016). "MiR-10b was up-regulated in malignant peripheral nerve sheath tumors (MPNSTs) and directly targeted the NF1 mRNA." (PMID 26646588, 2016). "Although NF1 is the most common disease, approximately 10% of the individuals with aberrant Nf1 develop MPNSTs (malignant peripheral nerve sheath tumors)." (PMID 27741517, 2016).
malignant peripheral nerve sheath tumor (continued). "With respect to NF-1, miR-10b and miR-34a have been shown to be up- and down- regulated in Malignant Peripheral Nerve Sheath Tumors, respectively while miR-10a also participates in the regulation of NF1 levels in these tumors." (PMID 23056445, 2012). "In a cohort of 448 NF1 patients in the UK, the overall risk of cancer was increased 2.7-fold compared to the general population, and malignant peripheral nerve sheath tumor (MPNST) was the leading cause of death." (PMID 21542925, 2011). "Specifically, a study has shown that SHP2 inhibition, using the SHP2 inhibitor SHP099, could efficiently reduce RAS-GTP loading, block RAS-mediated RAF/MEK/ERK signaling and abrogate tumor growth in NF1-malignant peripheral nerve sheath tumors (MPNSTs)." (PMID 41514664, 2026). "This study describes a malignant schwannoma of the sciatic nerve associated with NF-1 that had not metastasized since the first excision 10 years ago." (PMID 38013269, 2023). "Finally, NTRK rearrangements have been reported in other sarcomas, as 3/21 (14%) of malignant peripheral nerve sheath tumors (MPNST) with NF1 alterations, and very rarely (<1%) in other adults sarcoma subtypes." (PMID 37876963, 2023). "Malignant neurofibromas and other NF1-related tumors may warrant surgical excision and/or chemotherapy." (PMID 37959212, 2023). "In conjunction with additional tumor suppressors, the PRC2 subunits EED and SUZ12 (but not EZH2) are mutated in 85% of malignant peripheral nerve sheath tumors (MPNST) that develop in patients with NF1 mutations." (PMID 34617019, 2021). "Malignant peripheral nerve sheath tumors were detected in three of the 38 patients with NF1 whole gene deletions within the observed time period (type-1 group: n = 2; atypical group: n = 1), resulting in a prevalence of 7.9% (type-1 group: 7.4%; atypical group 9.1%), respectively." (PMID 33951044, 2021). "Previous studies showed that the anti-growth properties of farnesyl monophosphate prodrug farnesyltransferase inhibitors (FTIs) on human NF1 malignant peripheral nerve sheath tumor (MPNST) cells are potentiated by co-treatment with lovastatin." (PMID 38201517, 2023). "In NF1 studies, NF1-null cells derived from malignant peripheral nerve sheath tumors (MPNST) showed RAS cascade hyperactivation typical of NF1." (PMID 34229750, 2021). "Malignant peripheral nerve sheath tumor (MPNST) is an aggressive spindle cell sarcoma most commonly occurring in adults, that may be sporadic or arise in association with neurofibromatosis type 1 (NF1) or prior radiation." (PMID 33921435, 2021). "However, 5–10% of PNF patients could develop NF1-related malignant peripheral nerve sheath tumors (MPNSTs)." (PMID 32850344, 2020). "MPNST (previously known as neurogenic sarcoma, neurofibrosarcoma, or malignant schwannoma) is a relatively rare malignant tumor, accounting for 5–10% of all soft tissue sarcomas with an incidence rate of 0.001% in the general population and 4.6% in patients with NF1." (PMID 32631436, 2020). "Malignant peripheral nerve sheath tumor (MPNST) and angiosarcoma are rare tumors in children and adolescents and mostly occur in young patients in relation to NF1." (PMID 29138703, 2017). "For the vast majority of cases, the aetiology is unknown, although there are certain genetic associations, such as the 10% lifetime risk of malignant peripheral nerve sheath tumour (MPNST) in individuals with familial neurofibromatosis, caused by mutations in the NF1 gene." (PMID 20634933, 2010).
malignant peripheral nerve sheath tumor (continued). "Malignant perineurioma, also called “Malignant Peripheral Nerve Sheath Tumor with perineurial differentiation” represents an extremely rare variant of MPNST that is not related to NF1 or schwannomatoses." (PMID 35741273, 2022). "Aggressive malignant peripheral nerve sheath tumors (MPNST) lack NF1." (PMID 32674264, 2020). "To confirm that this decrease was not cell specific, we tested the effect of NSC124205 on the NF1-associated malignant peripheral nerve sheath tumors (MPNST) cell line ST8814, which is characterized by active RASWT." (PMID 32163428, 2020). "Although not classically associated with NF1, this tumour showed intense 18F-FDG uptake on PET imaging, illustrating the diagnostic overlap between benign and malignant peripheral nerve sheath tumours, particularly in patients with a genetic predisposition." (PMID 41002920, 2025). "CDK4/6 is crucial for the G1- to S-phase transition and abnormalities in CDK4/6 and the NF1 (a negative regulator of RAS activity) gene may contribute to neuroblastoma and malignant peripheral nerve sheath tumors." (PMID 38001644, 2023). "A definitive diagnosis of malignant peripheral nerve sheath tumor (MPNST) is challenging, especially in cases without neurofibromatosis 1 (NF1), because MPNST lacks specific markers on immunohistochemistry (IHC)." (PMID 34461930, 2021). "As malignant peripheral nerve sheath tumors have been sporadically reported in patients without NF-1, it is feasible that ANNUBP could also occur in patients without NF-1." (PMID 37252482, 2023).
pheochromocytoma (115 papers, 2005 to 2026). "A thorough physical examination was conducted, including orthostatic blood pressure measurements and blood glucose levels, due to the patient’s report of episodic overheating and known NF1 association with pheochromocytomas." (PMID 41141169, 2025). "Our case shows that hereditary pheochromocytoma associated with NF1 can present with persistent hypoglycemia." (PMID 40376359, 2025). "The pathogenesis of pheochromocytoma in NF1 involves a two-hit mechanism: the inherited NF1 mutation, followed by somatic loss of the second NF1 allele in chromaffin cells." (PMID 40741550, 2025). "NF1 was the first gene identified as responsible for a genetic disorder associated with pheochromocytoma." (PMID 39932063, 2025). "In this report, we describe a case of parathyroid carcinoma combined with pheochromocytoma in a patient with NF1, with the diagnosis confirmed by genetic mutation in the NF1 gene." (PMID 39932063, 2025). "Pheochromocytomas and paragangliomas (PPGLs) occur in up to 6.6% of NF1 patients, while germline and somatic NF1 variants are detected in 3% and one-fourth of sporadic cases of PPGLs, respectively." (PMID 39968302, 2025). "This case not only highlights the challenging diagnostic landscape of NF1 but also underscores the rarity of the co-occurrence of parathyroid carcinoma and pheochromocytoma within the context of NF1." (PMID 39932063, 2025). "Based on these findings, the patient was diagnosed with pheochromocytoma associated with NF1, alongside her existing type 2 diabetes mellitus and hypertension." (PMID 40741550, 2025). "The prognosis for NF1-associated pheochromocytoma is generally favorable, with low recurrence rates following surgical resection." (PMID 40741550, 2025). "Lack of neurofibromin results in increased RAS signaling and the development of NF-1-associated neoplasms such as peripheral nerve sheath tumors, pheochromocytoma, myeloid dysplasia and neurofibromas." (PMID 39682265, 2024). "Isolated deletion of SDHB caused an obesity phenotype that was similar to SDHC deletion, and codeletion of SDHB and NF1 resulted in development of SDHB‐deficient pheochromocytomas." (PMID 39399478, 2024). "As such, NF1-deficient pheochromocytomas, which are rare tumors developing from neural crest-derived chromaffin cells, exhibit RAS-mediated MEK/ERK1/2 hyperactivation." (PMID 35188187, 2022). "Pheochromocytoma, sarcoma, melanoma, breast cancer, leukemia, and gastrointestinal stromal tumors (GISTs) are also frequently associated to NF1." (PMID 35885913, 2022). "Cluster 2 PPGLs are built-up mostly by pheochromocytomas driven by variants in genes regulating kinase-driven pathways, including NF1, KIF1B, MAX, RET, TMEM127 and H-RAS." (PMID 35205664, 2022). "The proportion of patients with renovascular hypertension or hypertension caused by pheochromocytoma who also develop NF-1 has been analyzed previously." (PMID 34988040, 2021). "Of note, in cBioPortal, ATRX mutations were present in 4 (2.5%) of 162 pheochromocytomas/ paragangliomas, another tumor type that develops in NF1 patients." (PMID 31462295, 2019). "Both germline and somatic mutations in KIF1B gene have been found in pheochromocytoma, occasionally occurring in combinations with mutations in other genes, such as NF1, RET, VHL, and SDHx." (PMID 29504908, 2018). "Of all the somatic mutations identified in the study, 56% were located in NF1, showing that NF1 is frequently mutated in phaeochromocytomas/paragangliomas." (PMID 28637487, 2017). "This is in addition to the 26% (11/42) of sporadic paragangliomas and phaeochromocytomas that have lost one NF1 allele, associated with a reduction in NF1 mRNA level." (PMID 28637487, 2017). "NF1 is one of a number of known paraganglioma and phaeochromocytoma susceptibility genes, constitutional mutations in which are responsible for inherited tumour syndromes." (PMID 28637487, 2017).
pheochromocytoma (continued). "mTOR is a crucial downstream signal of both RAS and RET pathways, and is aberrantly activated in NF1-deficient malignant peripheral nerve sheath tumours, phaeochromocytomas and paragangliomas." (PMID 29166454, 2017). "A similar transcription profile is observed in pheochromocytomas in human patients carrying a germline mutation in the NF1 gene." (PMID 28187001, 2017). "Conversely, both germline and somatic mutations in this gene have been found in pheochromocytomas, occasionally occurring in combinations with mutations in other genes, such as NF1 or RET as well as VHL or SDHx." (PMID 28187001, 2017). "Almost a quarter (25/119) of the sporadic phaeochromocytomas/paragangliomas carried an inactivating NF1 mutation, of which 21/25 were associated with the loss of the wild-type allele." (PMID 28637487, 2017). "Inactivating mutations in NF1 are frequent in adrenal medullary tumors (pheochromocytomas) and it has been shown that NF1 is required for control of proliferation and differentiation in chromaffin cells." (PMID 25775093, 2015). "Various Nf1+/− mouse models show predisposition to tumour formation, including phaeochromocytomas, leukaemias and malignant peripheral nerve sheath tumours (MPNST), similar to the spectrum of NF1-associated malignancies observed in human counterparts." (PMID 25026295, 2014). "In keeping with the observation that NF1 individuals are at increased risk of developing phaeochromocytomas, these findings suggest that loss of NF1 function is a crucial event in the pathogenesis of both sporadic and NF1-associated phaeochromocytomas." (PMID 25026295, 2014). "A variety of endocrine tumors have been linked to NF1, with pheochromocytoma being the most common." (PMID 39932063, 2025). "In addition to the classic syndromes, MEN 2, VHL, and NF1, germline succinate dehydrogenase gene mutations (SDHx) are included as part of the pheochromocytoma syndromes." (PMID 40709162, 2025). "Autosomal dominant variants in the NF1 gene, located on chromosome 17q11.2, lead to diverse clinical manifestations, including café-au-lait macules, cutaneous neurofibromas, Lisch nodules, optic gliomas, seizures, pheochromocytomas, and osseous lesions." (PMID 41141169, 2025). "Although sporadic pheochromocytoma usually leads to impaired glucose tolerance and hyperglycemia, there is limited literature about the effect of hereditary pheochromocytoma on glucose metabolism, especially with NF1 taking into consideration the rarity of the association." (PMID 40376359, 2025). "In conclusion: resistant hypertension with café au lait spots may indicate pheochromocytoma, especially bilateral, suggesting an underlying genetic condition like NF1, warranting systematic screening." (PMID 39015197, 2024). "Finally, screening for pheochromocytoma should be systematic in the presence of NF1 because of the higher cardiovascular risk in these patients." (PMID 39015197, 2024). "Children with NF-1 (mutation of the NF1 gene) are also at an increased risk for pheochromocytomas." (PMID 36291833, 2022). "Finally, the cortical admixture cluster is characterized by pheochromocytomas with NF1 somatic mutations as well as MEN2-related tumors with RET germline mutations." (PMID 33768452, 2021). "Therefore, this procedure seems particularly recommended, when feasible, in VHL- and NF1-associated pheochromocytomas, and it can be performed in both adult and pediatric populations." (PMID 34025587, 2021). "Interestingly, a subset will develop less common NF1-associated tumors later in life, including neurofibrosarcoma, pheochromocytoma, and myeloid leukemia." (PMID 30302402, 2018). "Somatic mutations in the NF1 gene have been detected in 20–25% of sporadic pheochromocytomas." (PMID 28187001, 2017).